EEF1E1-BLOC1S5 (EEF1E1-BLOC1S5 readthrough (NMD candidate))
Gene: Protein-coding gene on chromosome 6 (8,015,726 to 8,102,530, reverse strand). Ensembl gene ENSG00000265818.
Genetic constraint (gnomAD): Missense variants: 116 observed, 113.42 expected, observed/expected ratio (o/e) 1.02, 90% interval 0.88 to 1.19. Synonymous variants: 46 observed, 49.06 expected, observed/expected ratio (o/e) 0.94, 90% interval 0.74 to 1.2.